C1orf202 (chromosome 1 open reading frame 202)
Gene: Protein-coding gene on chromosome 1 (244,729,701 to 244,731,015, reverse strand). Ensembl gene ENSG00000284188.
Homologues: Orthologues: mouse 4930527J03Rik (46% identical).